DCLK3 (doublecortin like kinase 3)
Synonyms: DCAMKL3; DCDC3C; KIAA1765; CLR; DCK3
Tractability: Small molecule: a high-quality ligand is known; it belongs to a druggable protein family. PROTAC: a small molecule that binds it is known.
Target class: CAMK protein kinase DCAMK1 family; Kinase; CAMK protein kinase group; Enzyme; Protein Kinase
Gene: Protein-coding gene on chromosome 3 (36,712,421 to 36,764,553, reverse strand). Ensembl gene ENSG00000163673.
Subcellular location: Cytoplasm; Nucleus
Subcellular location (Human Protein Atlas): Cytosol; Vesicles
Gene Ontology:
Molecular function: protein serine/threonine kinase activity; ATP binding; protein kinase activity; protein serine kinase activity
Cellular component: cytoplasm; nucleus
Genetic constraint (gnomAD): Loss-of-function variants: 30 observed, 42.95 expected, observed/expected ratio (o/e) 0.7, 90% interval 0.52 to 0.95. The upper end of that interval is the gene's LOEUF score, 0.95, which puts it in group 4 of 6, group 1 being the genes least tolerant of losing a copy. Missense variants: 789 observed, 844.7 expected, observed/expected ratio (o/e) 0.93, 90% interval 0.88 to 0.99. Synonymous variants: 370 observed, 316.69 expected, observed/expected ratio (o/e) 1.17, 90% interval 1.07 to 1.27.
Homologues: Orthologues: chimpanzee DCLK3 (99% identical), pig DCLK3 (79% identical), macaque DCLK3 (77% identical), rat Dclk3 (76% identical), mouse Dclk3 (73% identical), guinea pig DCLK3 (63% identical), rabbit DCLK3 (59% identical), tropical clawed frog dclk3 (32% identical), zebrafish dclk3 (29% identical), Caenorhabditis elegans F32D8.1 (15% identical). Paralogues in human: DCLK1 (28% identical), DCLK2 (28% identical), CAMK1 (16% identical), CAMK1D (15% identical), MYLK3 (15% identical), CAMK1G (15% identical), PNCK (15% identical), CAMK2D (15% identical), CAMK2A (14% identical), CAMK2G (14% identical), CAMK2B (14% identical), CAMKK2 (14% identical), and 10 more.
Diseases named in the same sentence as DCLK3 in open-access papers:
DCLK3 is named in the same sentence as 21 diseases in open-access papers, as found by Europe PMC text mining. Sharing a sentence is not in itself a finding about the gene and the disease. The quoted sentences say what the papers report.
colon cancer (2 papers, 2020 to 2024). "FuSiOn identified ten kinases (BMP2K, DCLK3, LIMK2, MAP2K5/MEK5, MAP3K3/MEKK3, ROS1, SIK2, TAOK2, ULK1, and ULK2) whose depletion mimicked the phenotypic effect of p62 depletion in HCT116 colon cancer cells." (PMID 33101709, 2020).
adenoma (1 paper, 2017). A neoplasm arising from the epithelium. "Interestingly, this elevation appeared to be correlated with the CRC progression: DCLK3 expression was at a comparable level in the healthy and adenoma tissues, and increased ∼2-fold in the stage I tumours and remained at this level during tumour malignancy (P=2.2 × 10−16, Kruskal–Wallis test)." (PMID 28195176, 2017).
Huntington disease (1 paper, 2025). Huntington disease (HD) is a rare neurodegenerative disorder of the central nervous system characterized by unwanted choreatic movements, behavioral and psychiatric disturbances and dementia. "Doublecortin-like kinase 3 (DCLK3), a member of this elusive group, has emerged for its involvement in neuroprotection in Huntington's disease and other neurodegenerative disorders." (PMID 40902973, 2025).
cancer (5 papers, 2011 to 2023). A tumor composed of atypical neoplastic, often pleomorphic cells that invade other tissues. "Here we identified a molecular function of this SNP in promoting cancer malignancy through a novel gene target named DCLK3." (PMID 28195176, 2017). "Other understudied kinases that score favorably in the majority of cancer cohorts include PKMYT1 (Tchem), DCLK3 (Tchem), BRSK1 (Tchem), ADCK5 (Tdark), and LMTK3 (Tbio)." (PMID 33205077, 2020). "These genes were not included in our original dataset either because they were not in the "Cancer Gene Census" category of COSMIC (MMP2, PIK3C3, TGM3, EPHA3) or because there was no crystal structure available (DCLK3)." (PMID 21575214, 2011).
tumor (3 papers, 2011 to 2023). "The consensus of the classifiers identifies DCLK3, MMP2, TGM3 as oncogenes and PIK3C3 and EPHA3 as tumor suppressors." (PMID 21575214, 2011). "Interestingly, we found that epithelial-to-mesenchymal transition (EMT)-related genes were highly correlated to the expression of DCLK3 in the healthy tissues (normalized enrichment score (NES)=2.50), which was enhanced in the tumour samples (NES=3.10)." (PMID 28195176, 2017). "Therefore, DCLK3 may promote EMT events and consequently drive tumour malignancy." (PMID 28195176, 2017).
psychiatric disorder (1 paper, 2026). A disorder characterized by behavioral and/or psychological abnormalities, often accompanied by physical symptoms. "Given its enrichment in stress‐sensitive regions and involvement in major psychiatric disorders, altered DCLK3 expression may reflect adaptive mechanisms to immune‐neural disruption and elevated allostatic load in MDD." (PMID 41173797, 2026).
DCLK3 also shares sentences with these, for which no sentence is quoted: colorectal cancer (2 papers); acute myeloid leukemia (1); Allergy (1); autism (1); autoimmune disease (1); bipolar disorder (1); bladder cancer (1); breast carcinoma (1); neurodegenerative disease (1); Obesity (1); sarcoma (1); schizophrenia (1); stomach carcinoma (1); triple-negative breast carcinoma (1); uterine carcinosarcoma (1).